HDAC6 (histone deacetylase 6)
Diseases named in the same sentence as HDAC6 in open-access papers (continued):
Sharing a sentence is not in itself a finding about the gene and the disease.
tumor (continued). "In line with the role of HDAC6 in modulating tumor immune microenvironment, combinational treatment with HDAC6 inhibitor and anti-PD-L1 antibody resulted in reduced tumor burden and improved survival." (PMID 36980292, 2023). "The acetylation of cortactin prevents its translocation to the cell periphery, blocks its association with F-actin, and impairs cell motility, while its deacetylation by HDAC6 increases tumor cell motility and hence their invasiveness." (PMID 38258065, 2023). "This study reveals the intriguing role and molecular mechanism of HDAC6 as a tumor promoter, and its inhibition represents a promising approach for anticancer therapy." (PMID 36639650, 2023). "Accordingly, HDAC6 inhibition has been shown to suppress tumor proliferation and induce apoptosis via the deactivation of AKT and ERK signaling." (PMID 38258065, 2023). "In experimental models of CRC, the HDAC6 gene knockdown and pharmacological HDAC6 inhibition reduced cell viability and migration of tumor cells by inhibiting the MAPK/ERK pathway." (PMID 38258065, 2023). "HDAC6 activity in tumor cells and immune cells in the TME has been shown to regulate the expression of tumor-associated antigens, MHC class I molecules, costimulatory molecules, and cytokines." (PMID 38258065, 2023). "In CRC, HDAC6 inhibitors have shown the potential to reduce tumor progression and enhance the therapeutic effect of other drugs." (PMID 38258065, 2023). "Ricolinostat (ACY-1215), an HDAC6 inhibitor, is currently being tested in multiple clinical trials to evaluate its enhanced tumor control in combination with chemotherapy (NCT01997840, NCT02787369, and NCT01583283)." (PMID 34976203, 2022). "A selective HDAC6 inhibitor decreases IL-1β and IL-6 production and PD-L1 expression in tumor cells." (PMID 35163049, 2022). "MPT0B451, a dual inhibitor of HDAC6 and tubulin inhibitor, suppressed tumor growth in HL-60 and PC-3 xenograft models." (PMID 36076996, 2022). "Based on previous studies, we concluded that the tumor microenvironment, HDAC6, and IL-13 play a very important role in the carcinogenesis of OSCC." (PMID 35732647, 2022). "HDAC6 is a tumor suppressor that inhibits Let-7i-5p to induce TSP1/CD47-mediated anti-tumorigenesis and phagocytosis of HCC." (PMID 35355509, 2022). "Considering the enhanced tumor control HDAC6 inhibition has provided in Phase I and Phase II clinical trials, HDAC6 inhibition proves once again to be a promising therapeutic and disease-modifying intervention for the treatment of CICD." (PMID 34976203, 2022). "The downregulation of either CD133 or HDAC6 was shown to increase β-catenin acetylation and degradation, which leads to decreased proliferation both in vitro and tumor xenograft growth in vivo." (PMID 36076996, 2022). "For example, in colon cancer, patient-derived tumor samples express significantly increased HDAC6 protein levels and this correlated with poor overall survival prognosis." (PMID 36012642, 2022). "HDAC6, a cytoplasmic deacetylase that accelerates tumor proliferation by triggering deacetylase activity, can bind to phosphorylated RIPOR2 and 14-3-3, forming a tripartite complex and disrupting its original function of forming a mitotic spindle." (PMID 36091054, 2022). "HDAC6 is mostly located in the cytoplasm to deacetylate non-histone substrates, such as the cytoplasmic protein substrates α-tubulin, cortactin, and heat shock protein 90, and HDAC6 is highly correlated with tumor malignancy." (PMID 36457493, 2022). "Several previous experiments have proven that selective inhibitors of HDAC6 synergistically improve anticancer activity via induction of tumor cell death." (PMID 36532053, 2022). "HDAC6 inhibition prevented the nuclear translocation of β-catenin, decreased c-myc expression, and inhibited tumor proliferation." (PMID 36076996, 2022). "It has been confirmed that the expression of HDAC6 is increased in a variety of tumor tissues and that HDAC6 can promote tumor development and metastasis." (PMID 36270986, 2022).
tumor (continued). "Recent studies have found that HDAC6 promotes oncogenic transformation and tumor formation by promoting anchorage-independent proliferation in transduced cells." (PMID 34485153, 2021). "HDAC6 levels were found to have higher expression in the three tumor cell lines compared to the normal human astrocytes (NHA) cell line." (PMID 34073238, 2021). "Collectively, these findings indicated that HDAC6 inhibition delays tumor growth in vivo and suggest that anti-tumor activity was mediated, at least in part, through its inhibition of EWSR1-FLI1 oncogene expression." (PMID 34345016, 2021). "When the balance between HAT and HDAC6 levels is dysregulated, the probability of tumor occurrence significantly increases due to an imbalance in the expression of oncogenes and tumor-suppressor genes." (PMID 34513696, 2021). "Tumor tissues showed overexpression of HDAC6 in comparison with the healthy tissues of the temporal and parietal zones." (PMID 34073238, 2021). "As explained, HDAC6 and the mesenchymal markers Snail and Slug were overexpressed in tumor tissue, as detected by RT-qPCR." (PMID 34073238, 2021). "High expression of HDAC6 in primary EWS tumor samples from patients correlates with a poor prognosis in two independent series accounting 279 patients." (PMID 34345016, 2021). "Preclinical studies revealed that HDAC6 silencing or inhibition results in impaired tumor growth in xenograft mouse models using NSCLC cells." (PMID 34552864, 2021). "We thus believe that, after the decrease in autophagy, cells cannot obtain all the energy they need for cell growth and proliferation, and, therefore, HDAC6 inhibition has a tumor-suppressing function." (PMID 34073238, 2021). "In fact, EWS cell lines were more sensitive to HDAC6 inhibition than other malignant cell lines and the non-tumor cell line hMSC (which are defined as the putative cells of origin for EWS)." (PMID 34345016, 2021). "Particularly, given the multitude of functions for HDAC6 including control of cell morphology, cell adhesion, cell migration and tumor metastasis." (PMID 34250905, 2021). "Intriguingly, numerous studies demonstrated that HDAC6 is a major regulator of autophagy and HDAC6-mediated autophagy is involved in the tumour cell destination under the administration of radiation and chemotherapy." (PMID 33744850, 2021). "Genetic or pharmacologic disruption of HDAC6 in CAFs delays tumor growth, inhibits tumor recruitment of MDSCs and Tregs, alters macrophage phenotype switch, and increases CD8+ and CD4+-T cell activation in vivo." (PMID 34337083, 2021). "HDAC6 is involved in tumor cell survival and growth, prompting the development of many selective inhibitors." (PMID 34944907, 2021). "Recently, WT161, as a selective HDAC6 inhibitor, has been shown to play anti-tumor effects on multiple myeloma, retinoblastoma and breast cancer." (PMID 33860796, 2021). "Based on the TCGA database data, HDAC6 expressions were grouped into high and low expression groups according to the median value of HDAC6 expression in each tumor." (PMID 34485153, 2021). "We next investigated the effects of using the HDAC6 inhibitor ACY-1215 in vivo on an HCC xenograft tumor model." (PMID 34868939, 2021). "By integration, 27 tumor modules were retained, and the final analysis showed that HDAC6 expression was downregulated in the combined 27 tumor modules." (PMID 34485153, 2021). "Considering the possible existence of non-tumor-related deaths during follow-up, we analyzed the relationship between HDAC6 expression levels and prognostic DSS (disease-specific survival) in 33 tumors of TCGA." (PMID 34485153, 2021). "As the three most relevant pathways to tumor development, single-gene enrichment allowed identifying HDAC6 as involved in the feedback of these pathways and involved in tumorigenesis based on these pathways." (PMID 34485153, 2021). "We evaluated the prognostic impact of HDAC6 expression levels in EWS tumor samples by immunohistochemistry (IHC)." (PMID 34345016, 2021).
tumor (continued). "Lentiviral-mediated knockdown of HDAC6 also slows tumor growth and promotes survival in an intracranial model of GBM." (PMID 33915983, 2021). "Combining the HDAC6-selective inhibitor tubacin with BTZ induces significant anti-tumor activity triggering c-Jun NH2-terminal kinase (JNK)-caspase signaling and endoplasmic reticulum (ER) stress." (PMID 33117804, 2020). "Analysis of mice with similar tumor burden indicated that the majority of T-cell changes elicited by silencing or inhibition of HDAC6 in vivo are likely secondary to decrease of tumor burden and immunomodulation of CLL B cells." (PMID 33329575, 2020). "A study by Li and colleagues also linked HDAC6 upregulation in BCAF to support an immunosuppressive TME; in which HDAC6 inhibition effectively restored the anti-tumour immunity of the TME toinhibit BC tumour growth." (PMID 33066013, 2020). "Prior studies in solid tumors show that selective HDAC6 inhibition can influence tumor cell immunogenicity and beneficially alter T-cell phenotypes, reducing suppressive populations and enhancing effector function." (PMID 33329575, 2020). "Our research showed that HDAC expression was high in both EC tissues and cell lines and that it promoted tumorigenicity and tumour progression in vitro, indicating an important role for HDAC6 in EC." (PMID 32107418, 2020). "First, HDAC6 inhibitors inhibit the expression of c-Myc oncoprotein, thus inhibiting tumor cells proliferation and promoting apoptosis." (PMID 32676030, 2020). "In this oncogenic context, the HDAC6 and Pin1 expression is regarded to involve in tumor progression and poor prognosis." (PMID 33162791, 2020). "Stimulating the ESCC cells with the Aurora A inhibitor Tripolin A reversed the effect of the over-expressed Prdx1 on p-Aurora A and HDAC6 proteins, and decreased p-Aurora A enhancement of cilium regeneration and inhibited the invasion of tumor cells." (PMID 32357862, 2020). "RTS-V5, a dual inhibitor that targets HDAC6 and the 20S subunit of the proteasome, also possesses potent and selective anti-tumor activity in leukemia and MM cell lines." (PMID 33117804, 2020). "In tumour progression, distant metastasis is a crucial process; thus, we applied a wound healing assay to assess the effect of HDAC6 on EC cell migration." (PMID 32107418, 2020). "Inhibition of histone deacetylase 6 (HDAC6) suppresses the growth of AT-rich interaction domain 1 (ARID1A) (a mutated epigenetic regulator) in tumors and modulates the tumor immune microenvironment." (PMID 32708748, 2020). "Mechanistically, HDAC6 inhibitors promote malignant tumor cell apoptosis by inhibiting protein degradation, reinvigorating anti-tumor immunity, and inhibiting cell survival signaling pathways." (PMID 32676030, 2020). "Data supports the anticancer properties of HDAC6; the deacetylation of microtubules in tumor cells suppresses angiogenesis, leading to the repression of metastasis." (PMID 31683808, 2019). "On the other hand, HDAC6 functions as a critical player to participate in the process of tumorigenesis through oncogenic cell transformation and tumor cell migration and invasion." (PMID 31652644, 2019). "Of note, combined treatment with the conventional cytotoxic drug 5-FU together with Tubastatin A, a HDAC6-specific inhibitor, resulted in a significant in vivo synergistic inhibitory effect on tumor growth through suppression of CRC stemness." (PMID 30804456, 2019). "HDAC6 is a key regulator of the expression of PD-L1 in tumor cells, and selective HDAC6i impairs the up-regulation of PD-L1 upon cytokine treatment." (PMID 30992475, 2019).
tumor (continued). "In particular, the selective inhibition of HDAC6 has been reported to decrease tumor growth in several malignancies." (PMID 30992475, 2019). "Inhibition of HDAC6 led to an increase in AKT activation (p-AKT) to control the survival of tumor cells." (PMID 30925865, 2019). "On the other hand, HDAC6 is necessary to maintain the tumor cells’ ability for anchorage-independent growth, cell cycle regulation, cell shape maintenance and cargo transport, and cellular stress response by regulating Hsp90." (PMID 31067680, 2019). "HDAC6 upregulation leads to tumour cisplatin resistance, and depletion of HDAC6 enhances cisplatin-induced DNA damage and apoptosis." (PMID 30787326, 2019). "In more recent work on melanoma, HDAC6 was also found to be regulating the expression of PD-L1 in a STAT3-dependent manner now established in multiple tumor types." (PMID 31067680, 2019). "Targeting HDAC6 can result in anti-tumor effects that are induced by the degradation of proteins and the inhibition of signaling pathways related to oncogenesis." (PMID 30987296, 2019). "An endogenous HDAC6-knockout cell is resistant to oncogenic transformation, and inactivation of HDAC6 can reduce tumour formation in mice." (PMID 30504808, 2018). "In our previous study, highly selective HDAC6 inhibitor 23BB has been designed, synthesized and evaluated for anti-tumor activity and safety in both solid and hematologic tumor models." (PMID 29632491, 2018). "To characterize tumor cell death induced by combined inhibition of HDAC6, 8 and 10, we quantified the fraction of cells in subG1 cell cycle phase after 72 h of TH34 treatment." (PMID 29947893, 2018). "Very likely, the compounds also inhibit HDAC6 in the tumor cells, as evidenced by a prominent increase in α-tubulin acetylation." (PMID 30064501, 2018). "In the present study, our aim was to investigate the novel HDAC6 inhibitor C1A, which has been shown to have anti-tumor properties, in combination with RGD4C-AAVP." (PMID 29690504, 2018). "In this review, we discuss how HDAC6 affects tumor development through its various substrates and the status of selected HDAC6 inhibitors." (PMID 30176876, 2018). "To conclude, we have shown that pharmacological inhibition of HDAC6 by C1A resolves autophagy induced by 3-MA and is cytotoxic to tumour cells alone or in combination with a proteasome inhibitor." (PMID 30318510, 2018). "Compound 23BB as a highly selective and potent HDAC6 inhibitor has been designed, synthesized and evaluated for anti-tumor activity in our lab." (PMID 29632491, 2018). "By inhibiting HDAC6, tubacin is predicted to engage both these HDAC6-dependent anti-tumor activities and the additional HDAC6-independent activities of tubacin identified here." (PMID 29423038, 2018). "Once the expression level of HDAC6 changes or its activity increases, it can lead to oncogenic cell transformation and tumor cell proliferation, invasion, metastasis, and mitosis." (PMID 30176876, 2018). "Aside from promoting cell migration and consequently tumour invasiveness, HDAC6 contributes to other oncogenic activities." (PMID 28668087, 2017). "HDAC6 can deacetylate α-tubulin increasing cell motility, a fundamental process in the development of tumor metastasis." (PMID 28704968, 2017). "Taken together, these results suggest that single agent anti-tumor activity of WT161 is HDAC6-independent." (PMID 29113288, 2017). "We previously published that [pazopanib + HDAC inhibitor] treatment reduced the expression level of HDAC6 in a wide variety of tumor cell types." (PMID 29137331, 2017). "As RanBPM is able to inhibit HDAC6-mediated cell migration, which promotes tumour invasiveness, this identifies a tumour suppressive function for RanBPM." (PMID 28668087, 2017). "Histone deacetylase 6 (HDAC6) is a microtubule-associated deacetylase that promotes many cellular processes that lead to cell transformation and tumour development." (PMID 28668087, 2017).
tumor (continued). "We further investigated the effects of HDAC5 or HDAC6 knockdown on A375 cells tumor growth when the cells were transplanted subcutaneously." (PMID 26747087, 2016). "Analyses of the quantified images indicated that the differences between tumor and normal tissues in total HDAC5 or HDAC6 levels protein levels (P < 0.0001) were all highly significant when comparing the 33 tumor samples with the 31 normal skin samples." (PMID 26747087, 2016). "Inactivation of HDAC6 decreases c-myc expression, leading to inhibition of tumor cell proliferation." (PMID 26848526, 2016). "Our analysis of tumor and matched non-tumor tissues from radical nephrectomies showed overexpression of class I and II HDACs (HDAC6 only in a subset of patients)." (PMID 27506904, 2016). "HDAC5 or HDAC6 knockdown in A375 cells induced apoptosis, arrest of cell cycle and tumor growth in nude mice." (PMID 26747087, 2016). "HDAC5 and HDAC6 knockdown induced a 25 and 98 % reduction in the tumor volume of A375 cells, respectively." (PMID 26747087, 2016). "We investigated mechanisms responsible for survival of tumor cells treated with a HDAC6 inhibitor and report that HDAC6 inhibition promotes inactivating PTEN phosphorylation and consequently activation of AKT." (PMID 27362804, 2016). "In contrast, the class-II HDACi Tubacin and a HDAC6 specific HDACi had little impact on either the TH-MYCN cells or the control tumor cell lines." (PMID 27471639, 2016). "The human histone deacetylase isoform 6 (HDAC6) has been demonstrated to play a major role in cell motility and aggresome formation, being interesting for the treatment of multiple tumour types and neurodegenerative conditions." (PMID 27404291, 2016). "Cytoplasmic HDAC6 has been reported to interact with α-tubulin, cortactin, heat shock protein 90, β-catenin, and peroxiredoxins and to survive to regulate tumor growth, apoptosis, and migration." (PMID 26388610, 2015). "Further, HDAC6 has also been shown to be required for efficient oncogenic RAS-associated transformation and tumor formation." (PMID 25340937, 2014). "This miRNA has two validated target genes, HDAC6 and FGF20, which have both been implicated in tumor development." (PMID 23890084, 2013). "The results showed that knockdown of HDAC6 significantly reduced tumor volume and weight, indicating that HDAC6 is essential to promote tumor growth in a xenograft mouse model." (PMID 22957056, 2012). "Previous studies showed that inhibition of HDAC6 induces DNA damage and sensitizes transformed cells to anti-tumor agents such as etoposide and doxorubicin." (PMID 22957056, 2012). "Since tumor growth was significantly reduced in H292 HDAC6 knockdown xenografts, it will be difficult to study cisplatin sensitivity in vivo using this cell line." (PMID 22957056, 2012). "Lastly, depletion of HDAC6 in H292 xenografts rendered decreased tumor weight and volume and exhibited increased basal apoptosis compared with the controls in a xenograft mouse model." (PMID 22957056, 2012). "Among them, HDAC6 has been shown to be required for efficient oncogenic transformation and tumor formation." (PMID 21044318, 2010). "Among them, AKOS030273637 (Compound 10), featuring a benzyl 4-[4-(hydroxyamino)-4-oxobutylidene]piperidine-1-carboxylate scaffold, was confirmed to inhibit HDAC6 enzymatic activity, with a significant anti-tumor effect against MM cell lines, including those resistant to standard therapies." (PMID 41011174, 2025). "Last, the tumor‐promoting effect of the METTL3/HDAC6 axis was verified with clinical data." (PMID 39535388, 2025). "HDAC1, HDAC2, and HDAC6-mediated deacetylation of Sp1 has been reported to enhance cell proliferation and stem cell maintenance, which may contribute to tumor progression and TMZ resistance." (PMID 40450300, 2025).